PDIA3 (protein disulfide isomerase family A member 3)
Diseases named in the same sentence as PDIA3 in open-access papers (continued):
Sharing a sentence is not in itself a finding about the gene and the disease.
tumor (continued). "Additionally, the upregulation of PDIA3 protein expression in primary tumor tissues compared to normal tissues was verified using the CPTAC protein database (P = 1.6E-27)." (PMID 37909009, 2023). "In this study, we analyzed the expression of CCT2 and PDIA3 by IHC staining in 46 SC/ASC samples as well as in 80 AC samples, and found that both CCT2 expression and PDIA3 expression were significantly correlated with tumor progression and shorter survival time for patients with SC/ASC and AC." (PMID 23782473, 2013). "The results from TIMER demonstrated a positive correlation between PDIA3 and tumor-infiltrating CD8 T cells and macrophages, and a negative correlation with tumor-infiltrating CD4 T cells." (PMID 37909009, 2023). "PGAM-1, HSPD1, PDIA3 and SSP411 were overexpressed in tumor tissues compared to the matched non-tumor tissues." (PMID 23118872, 2012).
infection (19 papers, 2011 to 2025). The state of being infected such as from the introduction of a foreign agent such as serum, vaccine, antigenic substance or organism. "The PDIA3 gene has been identified to play an important role in the infection of C. hongkongensis infected under V. harveyi." (PMID 40028181, 2025). "Other host proteins that were not recurring across the 15 interactomes but common in other interactomes such as HYOU1, PDIA3, HSPA9, CTSS, etc., have been already also found deregulated upon pathogenic infection." (PMID 30815000, 2019). "Quantification of OAS1 isoforms relative to PDIA3 revealed a significant increase in the correlation of p46, but not p42, to PDIA3-positive membranes during infection, suggesting that p46 is recruited to sites of WNV replication." (PMID 34342578, 2021). "PDIA3 forms S–Ss between cysteine residues in HA and is significantly upregulated in mouse lungs following infection by various strains of IAV, as well as in human lung epithelial cells following infection with a pandemic, although not a seasonal strain of influenza." (PMID 34122136, 2021).
neurodegenerative disease (10 papers, 2015 to 2023). A disorder of the central nervous system characterized by gradual and progressive loss of neural tissue and neurologic function. "Additionally, a hypothesis suggests that the role of ERp57/PDIA3 in neurodegenerative diseases may be linked to its function as a receptor for VD." (PMID 38069206, 2023). "Although PERK is a controversial target in the context of neurodegenerative diseases, PDIA3 has been reported as an inhibitor of the PERK signaling pathway, suppressing PERK activation via PDI reduction." (PMID 36769334, 2023). "A variety of studies are exploring the involvement of the protein disulfide isomerase isoform A3 (PDIA3) in the response to several types of stress in different neurodegenerative diseases, including AD, Parkinson’s disease, and Prion Diseases." (PMID 36769334, 2023). "Given the known potential roles of PDIA3 in aging, as well as in neurodegenerative diseases, we longitudinally analyzed the changes of PDIA3 protein levels in some limbic brain regions of Non-Tg and 3×Tg-AD mice, which develop both Aβ and tau pathologies in an age-dependent manner." (PMID 36769334, 2023). "Since PDIA3 is deregulated in many neurodegenerative diseases, we conducted a longitudinal study to evaluate whether the altered PDIA3 expression observed over time in 3×Tg-AD mice by a dot blot analysis, was related to a different cellular distribution in the limbic areas analyzed." (PMID 36769334, 2023).
neurological disease (6 papers, 2022 to 2025). "Other studies have also indicated changes associated with the PDIA3 gene in neurological diseases." (PMID 38534785, 2024). "A protective function of ERp57/PDIA3 in nervous system diseases was suggested by using a Tat-ERp57/PDIA3 fusion protein (where the Tat domain was used to deliver the protein without any cellular toxicity)." (PMID 35109791, 2022). "Additionally, the ERS-related proteins were downregulated following anti-TNF-α and anti-IL-1β treatment, including those implicated in neurological disorders such as HYOU1, PDIA4, and PDIA3." (PMID 40338234, 2025). "Potential inhibitors of the interaction between vitamin D3 and ERp57/PDIA3 could be used to discriminate their role in neurological disease." (PMID 35109791, 2022).
bacterial infection (2 papers, 2021 to 2023). "DRAM1 was also in close proximity to FAM49B (related to bacterial infection), THBS1 (related to autophagy), TAGLN2 (related to phagocytosis), and PDIA3 (related to autophagy), which displayed higher expression levels in and around the cell nucleus." (PMID 37919720, 2023). "The expression of B2m, Ctsl, Calr, and Pdia3 suggests efficient antigen processing and presentation process, and the upregulation of Rac1, and Cd14 indicats the involvement of TLR2 and TLR4, which are essential for Th1/Th17 responses elicited by wPVs or bacterial infection." (PMID 34759909, 2021).
cardiovascular diseases (2 papers, 2012 to 2024). "For instance, the PDIA3 gene, associated with the folding and oxidation of proteins, has been targeted for developing several zinc-related FDA-approved drugs for treating cardiovascular diseases." (PMID 38521789, 2024).
hematologic disorder (1 paper, 2022). A disease involving the hematopoietic system. "Our data suggest that GRP78, CALR, PDIA3 and GPI released from irradiated MSC act as mediators of genetic instability in human CD34+ cells with potential implications for radiation-induced hematologic disorders." (PMID 35740549, 2022).
respiratory diseases (1 paper, 2022). "PDIA3 catalyzes oxidative modifications of numerous proteins, including proteins that are mediators of respiratory diseases." (PMID 35162999, 2022).
PDIA3 also shares sentences with these, for which no sentence is quoted: adenocarcinoma (4 papers); scrapie (4); esophageal squamous cell carcinoma (3); lung adenocarcinoma (3); prostate adenocarcinoma (3); uveal melanoma (3); asthenozoospermia (2); astrocytomas (2); lymphoid neoplasm (2); medulloblastoma (2); metastatic disease (2); ovarian serous cystadenocarcinoma (2); rectal adenocarcinoma (2); renal carcinoma (2); skeletal diseases (2); skin Cutaneous Melanoma (2); sporadic CJD (2); acute lymphoid leukemia (1); acute T-cell leukemia (1); adenosquamous carcinoma (1); adrenocortical carcinoma (1); Alport syndrome (1); arteriosclerosis (1); asthma (1); autoimmune hemolytic anemia (1); autoimmune pancreatitis (1); B-cell lymphoma (1); bladder urothelial carcinoma (1); brain tumor (1); breast adenocarcinoma (1).
A further 61 diseases each share a sentence with PDIA3 in 1 paper.